UCA1 (urothelial cancer associated 1)
Diseases named in the same sentence as UCA1 in open-access papers (continued):
Sharing a sentence is not in itself a finding about the gene and the disease.
breast cancer (continued). "UCA1 can up-regulate the expression of PTP1B in breast cancer cells by sequestering miR-206 at post-transcriptional level, which can inhibit PTP1B expression by binding to the 3′UTR of its mRNA." (PMID 31695578, 2019). "The results also suggested that UCA1-induced PTP1B expression facilitated the proliferation of breast cancer cells." (PMID 31695578, 2019). "For example, in breast cancer, UCA1 has been shown to induce drug resistance to tamoxifen in several recent studies." (PMID 31695578, 2019). "We conclude that UCA1 can up-regulates PTP1B to enhance cell proliferation through sequestering miR-206 in breast cancer." (PMID 31695578, 2019). "Our data indicate a novel model to depict an IMP1/UCA1/miR-122-5p interaction during the progress of breast cancer cell invasion." (PMID 29669595, 2018). "To explore the biological significance of IMP1-regulated UCA1 expression, we precipitated MS2 hairpin-tagged lncRNA UCA1 in breast cancer cells to identify UCA1-associated miRNAs." (PMID 29669595, 2018). "RNA pull-down and RNA binding protein immunoprecipitation (RIP) were performed to confirm the molecular interactions of IMP1-UCA1 and UCA1-miR-122-5p involved in breast cancer cells." (PMID 29669595, 2018). "Epigenetic inhibition of UCA1 in breast cancer cells was mediated by the Special AT-rich sequence Binding-protein 1 (SATB1)." (PMID 30441811, 2018). "Although recent work has shown that TGF‐β induced UCA1 expression in breast cancer through downstream Smad2/3 signaling 20, the detailed mechanisms underlying Smad2/3‐mediated regulating of UCA1 expression were not revealed." (PMID 30410864, 2018). "We next examined the biological function of IMP1 in the regulation of UCA1-mediated breast cancer cell invasion." (PMID 29669595, 2018). "Studies have shown that knockdown of long noncoding RNA UCA1 suppressed the tamoxifen resistance of breast cancer cells through inhibiting wnt/β-catenin pathway." (PMID 30442884, 2018). "In the present study, we show that in breast cancer cells IMP1 binds to the ACACCC motifs of lncRNA UCA1 via the KH34 domain of the protein." (PMID 29669595, 2018). "Three UCA1 isoforms of 1.4, 2.2 and 2.7 kb in length have been detected in human tumors, among which the 1.4-kb isoform is a major isoform in breast cancer cells and has been shown to promote breast tumor progression." (PMID 29669595, 2018). "Since then, high expression of UCA1 has been observed in a number of human cancers, including colorectal cancer and breast cancer, suggesting a common oncogenic role of UCA1 in tumorigenesis." (PMID 29669595, 2018). "Binding of UCA1 to heterogeneous nuclear ribonucleoprotein I (hnRNPI) in breast cancer cells resulted in the decreased stimulation of the p27 promoter by hnRNPI." (PMID 30441811, 2018). "UCA1 interaction with PTBP1 had been described in breast cancer cells, where the interaction induced IRES-mediated translation initiation of p27 mRNA to promote cancer cell proliferation." (PMID 30349036, 2018). "RT-qPCR and RNA sequence assays were used to investigate the expression of UCA1 and miRNAs in breast cancer cells in response to IMP1 expression." (PMID 29669595, 2018). "Here, we report that in breast carcinoma cells, the insulin-like growth factor 2 messenger RNA binding protein (IMP1) binds to lncRNA urethral carcinoma-associated 1 (UCA1) and suppresses the UCA1-induced invasive phenotype." (PMID 29669595, 2018). "Mechanistically, UCA1 is thought to promote tamoxifen resistance in breast cancer cells by activating the AKT/mTOR signaling pathway, where several additional miRNAs are thought to be involved in the chemoresistance phenomenon." (PMID 29299178, 2017). "AHIF, MALAT1, SNHG6, UCA1 expression levels increased in breast cancer tissues compared with their counterpart adjacent tissues, while AFAP1-AS1, PVT1, HYMAI had lower expression in tumors." (PMID 28938549, 2017).
breast cancer (continued). "For example, UCA1 can drives breast cancer cell growth and apoptosis by inhibiting tumor suppressive miRNA-143." (PMID 27893417, 2017). "Together, these findings reveal that lncRNA UCA1 induces chemoresistance to tamoxifen through different molecular pathways, and regulates several other miRNAs involved in breast cancer." (PMID 29299178, 2017). "UCA1 is a common molecular marker for lymph node metastasis and prognosis in various cancers including breast cancer, esophageal cancer, and pancreatic cancer." (PMID 28108736, 2017). "Huang reported that UCA1 competitively inhibits the suppressive effect of hnRNP on p27, which significantly promotes breast cancer proliferation." (PMID 28209917, 2017). "A recent in vitro study reported that incubation of exosomes with lncRNA UCA1 from the tamoxifen-resistant breast cancer cell line LCC2 with the tamoxifen-sensitive breast cancer cell line MCF-7 resulted in acquired drug resistance." (PMID 28969100, 2017). "Further, depletion of UCA1 was shown to improve the sensitivity of breast cancer cells to tamoxifen, consistent with its role in tamoxifen resistance." (PMID 29299178, 2017). "Conversely, transcription factor SATB1 represses lncRNA UCA1 expression in breast cancer cells by directly binding to the promoter and 3.0 kb upstream regions of UCA1 and closing the chromatin structure, thereby blocking transcription." (PMID 28969100, 2017). "It has also been shown to induce EMT in breast cancer by enhancing Wnt/beta-catenin signalling pathway, and again silencing of UCA1 resulted in increased expression of E-cadherin but decreased expression of N-cadherin, Vimentin and Snail." (PMID 28430163, 2017). "UCA1 binding to miR-143 was proved in breast cancer, where UCA1 was able to modulate cell growth and apoptosis by downregulating miR-143: this in turn led to upregulation of BCL2 (BCL2, apoptosis regulator) and ERBB3 (erb-b2 receptor tyrosine kinase 3)." (PMID 29147648, 2017). "Several studies have identified UCA1 as an oncogenic factor in several different cancers, including breast cancer." (PMID 29299178, 2017). "Recently, lncRNAs such as lncRNA-ATB, GAS5, HOTAIR, CCAT2, H19, BCAR4, UCA1, LncRNA-ROR and LncRNA-ARA have been implicated in resistance to chemotherapy in breast cancer patients." (PMID 29299178, 2017). "It has been reported that UCA1 enhances tamoxifen resistance in breast cancer cells via regulating AKT/mTOR signaling pathway." (PMID 29221199, 2017). "Established the contribution of lncRNA UCA1 on Wnt/β-catenin signaling activity using in vitro model, we further examined the nuclear β-catenin level in different stages of breast cancer patients." (PMID 27977766, 2016). "To examine the effect of lncRNA UCA1 on tamoxifen sensitivity of breast cancer cells, we compared the survival rate of breast cancer cells transfected with scramble control or small interfering RNA targeting lncRNA UCA1." (PMID 27977766, 2016). "In breast cancer, UCA1 modulates cell growth and apoptosis, at least partially by interacting with miR-143, a microRNA with a tumor suppressive role in breast cancer and colorectal cancer." (PMID 27608009, 2016). "In conclusion, we demonstrate that the knockdown of lncRNA UCA1 inhibits the Wnt/β-catenin signaling and increases the tamoxifen sensitivity by promoting the apoptosis of breast cancer cells when exposed to tamoxifen." (PMID 27977766, 2016). "Our result demonstrated that the expression of lncRNA UCA1 was significantly higher in the stages III + IV group than that in the stage I + II group (p<0.05), indicating a positive correlation between the severity of breast cancer and the expression of UCA1." (PMID 27977766, 2016). "Recent studies also demonstrated that the expression of UCA1 was increased in the breast cancer, which promoted the growth of breast cancer by suppressing the tumor suppressor p27, highlighting the important roles of UCA1 in breast cancer development." (PMID 27977766, 2016).
breast cancer (continued). "In consistent with the previous study, we also detected significantly increased expression of lncRNA UCA1 in the breast cancer group compared with the normal control group (p<0.05)." (PMID 27977766, 2016). "Firstly we detected the lncRNA UCA1 expression in all human breast cancer tissues enrolled in this study." (PMID 27977766, 2016). "Taken together, these data indicated that lncRNA UCA1 contributes to the resistance of breast cancer cells to tamoxifen." (PMID 27977766, 2016). "Next, we investigated the effect of lncRNA UCA1 on the migration ability of breast cancer cells using transwell assay." (PMID 27977766, 2016). "Since its first description in 2006, several studies have confirmed UCA1 to be a biomarker for urothelial carcinoma and studied its expression in other cancers, including colorectal and breast cancers." (PMID 26191476, 2015). "In vitro, ectopic expression of UCA1 enhances breast cancer cell growth, while UCA1-siRNA suppresses growth, leading to the accumulation of cells in G1 phase, as well as decreased Ki67 staining in tumors from mice." (PMID 25400658, 2014). "Therefore, this study aims to investigate the expression patterns and potential regulatory relationships between key transcription factors (FOXC2, SNAIL, and ZEB) and oncogenic lncRNAs (HOTAIR, MALAT1, and UCA1) in metastatic breast cancer stem cells." (PMID 40781106, 2025). "Furthermore, exosomal lncRNA HOTAIR, UCA1 and H19 in drug-resistant breast cancer and exosomal lncRNA UCA1 in drug-resistant ovarian cancer seem to be promising diagnostic biomarkers and molecular targets to reduce drug resistance." (PMID 39925739, 2025). "By employing the search terms “UCA1”, “breast cancer”, “endometrial cancer”, “ovarian cancer”, “cervical cancer”, “vaginal cancer”, and “vulvar cancer” in the PubMed database for the literature review, we identified a total of sixty-three relevant research articles published between 2014 and 2024." (PMID 38534790, 2024). "Conversely, UCA1 upregulation enhanced the invasiveness of breast cancer cells." (PMID 38277283, 2024). "Similarly, lncRNA UCA1 is highly expressed in paclitaxel-resistant breast cancer tissues and MCF-7 cells, and it was further confirmed that UCA1 mediates paclitaxel resistance via regulation of the miR-613/CDK12 axis." (PMID 37569629, 2023). "In addition, UCA1 significantly enhanced the resistance of breast cancer cells to tamoxifen by activating CAMP responsive element binding protein (CREB) through PI3K/AkT-dependent pathway." (PMID 37901333, 2023). "Inhibiting the expression of the lncRNA UCA1 may prove useful in the therapeutic management of breast cancer." (PMID 37245177, 2023). "Besides breast cancer, overexpression of LncRNA UCA1 also accelerated Acute myeloid leukemia (AML) development by regulating METTL14-mediated CXCR4 and CYP1B1 mRNA." (PMID 37365581, 2023). "Tamoxifen treatment in ER+ breast cancer cells may induce lncRNA UCA1 expression in a HIF1α-dependent manner, leading to tamoxifen resistance overtime." (PMID 37583933, 2023). "Conversely, in breast cancer cells, IMP1 binds to the ACACCC motif of lncRNA UCA1 through the KH34 structural domain of the protein, destabilizing UCA1, promoting the decay of UCA1, and causing suppression of the UCA1-induced invasive phenotype." (PMID 36052258, 2022). "However, the role of HIF-1α in the regulation of UCA1 in breast cancer has rarely been investigated." (PMID 34054950, 2021). "Moreover, high expression of UCA1 activated the wnt/β‐catenin signaling pathway, enhanced the nuclear translocation of β‐catenin and promoted invasion in breast cancer." (PMID 34527584, 2021). "UCA1 is one of the HIF-1α-regulated lncRNAs in hypoxic breast cancer." (PMID 34054950, 2021). "Similarly, it was denoted that ectopic expression of UCA1 desensitizes breast cancer cells to tamoxifen along with an insufficient activation of caspase-3." (PMID 34298879, 2021).
breast cancer (continued). "UCA1 was also reported to be upregulated in breast cancer compared to matched normal tissues." (PMID 34054950, 2021). "In addition, UCA1 expression is significantly overexpressed in breast cancer tissues compared to matched normal cells." (PMID 34054950, 2021). "UCA1 knockdown in hypoxia inhibits breast cancer proliferation and induces apoptosis." (PMID 34054950, 2021). "Here, we show that UCA1 is upregulated in a number of hypoxic (1% O2) breast cancer cells." (PMID 34054950, 2021). "AKT signaling pathway has a vital role in cell cycle distribution, cell growth,apoptosis and survival of human cancer, and UCA1 could regulate cell cycle progression in breast cancer via PI3K/AKT-dependent pathway." (PMID 33743811, 2021). "LncRNA UCA1 promotes EMT by enhancing Wnt/β-catenin signalling in breast cancer cells." (PMID 32913459, 2020). "UCA1 is downregulated in breast cancer and promotes disease progression." (PMID 32486413, 2020). "Investigators analyzed altered lncRNAs in breast cancer induced by conditioned medium from cultured human THP-1 macrophages, and they found that a large number of lncRNAs were changed; including lncRNA UCA (urothelial cancer associated 1)." (PMID 31777603, 2019). "Our finding provides new insights into the mechanism of breast cancer mediated by UCA1." (PMID 31695578, 2019). "Our finding provides new insights into the mechanism of breast cancer regulation by UCA1, which could be a potential target for breast cancer treatment." (PMID 31695578, 2019). "Exosomes promote drug resistance to tamoxifen in breast cancer by regulating the transfer of UCA1." (PMID 31777598, 2019). "Human urothelial carcinoma associated 1 (UCA1) lncRNA has a role in cell proliferation, apoptosis, and cell cycle progression regulation and an increased UCA1 expression level was reported first in urothelial cancer and also reported for breast cancer and CRC patients." (PMID 31694571, 2019). "This gives new insights on UCA1 regulation in breast cancer." (PMID 31695578, 2019). "UCA1 has also been shown to induce drug resistance to tamoxifen in breast cancer treatment." (PMID 31695578, 2019). "UCA1 has been reported to bind to several miRNAs in different cancer cells, which include miR-193a in non-small cell lung cancer, miR-216b in hepatocellular cancer, miR-18a in breast cancer cells, miR-204 in colorectal cancer, etc." (PMID 31695578, 2019). "Our findings take a further step into the mechanism of lncRNA UCA1-mediated breast cancer growth." (PMID 31695578, 2019). "In this study, we aim to study whether lncRNA UCA1 promotes the development of breast cancer by targeting PTP1B through miR-206." (PMID 31695578, 2019). "In addition, UCA1 was found to be epigenetically regulated by special AT-rich sequence binding protein 1 to regulate breast cancer cell growth and survival." (PMID 31596734, 2019). "Overexpression of UCA1 was detected in human primary breast cancer." (PMID 31777603, 2019). "Since IMP1 expression resulted in decreased levels of UCA1 in breast cancer cells, we investigated whether IMP1 could regulate UCA1 stability." (PMID 29669595, 2018). "Based on several studies, it is thought that UCA1 either manipulates the mTOR signaling pathway and/or exploits an miR-18a-HIF1α feedback loop as well as the Wnt/β-catenin signaling pathway to confer tamoxifen resistance in breast cancer." (PMID 29299178, 2017). "Over-expression of UCA1 acts as a molecular sponge and down-regulates miR-18a by associating with the Ago2-containing RNA-induced silencing complex (RISC), supporting the idea that ER-positive breast cancer cells can acquire tamoxifen resistance via a UCA1-miR-18a-HIFα feedback loop." (PMID 29299178, 2017). "The most-top ranked lncNA that is related to breast cancer is UCA1." (PMID 29108274, 2017).
breast cancer (continued). "Besides, a recent study reported that UCA1 facilitates EMT of breast cancer cells via enhancing Wnt/β-catenin signaling pathway." (PMID 29221199, 2017). "In breast cancer the 1.4 kb isoform of UCA1 is up-regulated (20-fold) and exerts its oncogenic effect, in part by the formation of a UCA1-hnRNP I (heterogeneous nuclear ribonucleoprotein I) complex, which results in suppression of p27 expression and promotes cancer cell proliferation." (PMID 29299178, 2017). "The transcriptional complex is composed of Hippo pathway effectors (TAZ/YAP/TEAD) and members of the transforming growth factor-β (TGF-β) pathway (SMAD2/3) that are recruited to the UCA1 promoter and synergistically induce its expression in breast cancer cells after TGF-β treatment." (PMID 28969100, 2017). "Moreover, lncRNA UCA1, an oncogene in breast cancer, affects breast cancer cell growth and apoptosis through downregulation of mir-143." (PMID 28938549, 2017). "We also used the Spearman's Rank-Order Correlation analysis to define the correlation between the nuclear β-catenin level and the expression of lncRNA UCA1 in human breast cancer tissues, and the results indicated a highly positive correlation (R2 = 0.77, p<0.001)." (PMID 27977766, 2016). "In line with this, when we divided all 54 patients into two groups according to the median value of lncRNA UCA1, we found that the survival rate dropped in breast cancer patients with high expression level of lncRNA UCA1 when compared with those with low expression of UCA1." (PMID 27977766, 2016). "We found that the expression of UCA1 positively correlated with the pathological grade and mortality of breast cancer patients, moreover, expressions of UCA1 was increased significantly in the tamoxifen-resistant cell lines compared with the wild type parental cells." (PMID 27977766, 2016). "In addition, the effects of UCA1 on cell proliferation and invasiveness in our study were similar to those of Nodal in breast cancer." (PMID 26160838, 2015). "In breast cancer, UCA1 is upregulated and displays oncogenic properties." (PMID 25400658, 2014). "Interestingly, UCA1 was upregulated in MDA-MB-231 TNBC cells compared to matched normal tissues under hypoxic conditions, suggesting that increased UCA1 expression may contribute to the increased migration and invasion of hypoxic breast cancer cells." (PMID 39594803, 2024). "UCA1 is regulated by the activation of hypoxia-inducible transcription factor (HIF-1) and has been implicated in the promotion of development and proliferation of breast cancer cells through numerous pathways by regulating cell-cycle proliferation and tumor metastasis and apoptosis." (PMID 39594803, 2024). "Besides, UCA1 also promotes breast cancer cells to resist tamoxifen by activating AKT/mTOR axis." (PMID 33565716, 2021). "We observed that UCA1 could up-regulate PTP1B expression in breast cancer cells." (PMID 31695578, 2019). "Therefore, UCA1 may serve as a therapeutic target for developing a potential treatment against breast cancer, particularly in tamoxifen-resistant patients." (PMID 29299178, 2017). "Taken together, our data highlights the pivotal role of UCA1-Wnt/β-catenin signaling pathway in the tamoxifen resistance in breast cancer, which could be targeted to improve the effectiveness and efficacy of tamoxifen treatment in breast cancer." (PMID 27977766, 2016). "Although, increase in expression of lncRNA UCA1 with worse grade of breast cancer may not have a definite association of lncRNA UCA1 with tamoxifen resistance, since all these samples were taken before treatment." (PMID 27977766, 2016). "An isoform of UCA1 is associated with doxorubicin resistance in a squamous cell carcinoma line, but it is not known whether this applies to breast cancer." (PMID 25400658, 2014).